RAG1 (recombination activating 1)
Diseases named in the same sentence as RAG1 in open-access papers (continued):
Sharing a sentence is not in itself a finding about the gene and the disease.
colitis (continued). "In this assay, adoptive transfer of CD45.1+ WT CD4+CD25− effector T cells into CD45.1+ RAG-1-KO mice led to colitis, and co-transfer of CD45.2+ Treg cells that are congenically different from effector T cells was used to evaluate the suppressive activity of Treg cells." (PMID 33024109, 2020). "We observed that Kcnt2−/−Rag1−/− mice did not affect lymphocytes infiltration, colon injury, body weight loss and colitis scores compared with Kcnt2+/+Rag1−/− mice, suggesting Kcnt2 has no influence on innate colitis induction." (PMID 32796851, 2020). "We have used both iTreg induced ex vivo and Treg differentiated in colitis in RAG1 KO mice." (PMID 30631042, 2019). "In contrast, transfer of RORγt-deficient T cells into RAG1-null mice fails to augment IL-17 expression and does not cause colitis, indicating a crucial role for RORγt-expressing Th17 cells in colitis." (PMID 30804707, 2019). "To examine whether the inflammasome sensor NLRP3 may also be involved in this process, we evaluated the course of colitis in Rag1−/− mice receiving naïve CD4+ T cells sorted from the spleen of Nlrp3−/− mice." (PMID 31379813, 2019). "Furthermore, CD40-treated Gpr183−/−Rag1−/− mice developed only mild colitis with an inflammation score similar to that of PBS-treated Gpr183+/+Rag1−/− mice." (PMID 29343433, 2018). "More importantly, under syngeneic conditions, RORγt- and BATF-deficient T cells comparably failed to induce colitis upon transfer into lymphopenic Rag1−/− mice." (PMID 29910804, 2018). "Rag-1-/- mice have been shown to exhibit transient colitis in response to CR infection." (PMID 30383855, 2018). "To determine whether CerS6 splenocytes differed in their ability to induce colitis, we isolated naïve CD4+CD45RBhi cells from either wild type or CerS6-deficient mice and adoptively transferred them into RAG1-deficient recipients." (PMID 29138469, 2017). "As a result, DEXA inhibited colitis induction may have been due to reduced donor CD4+ T cell survival in the Rag1-ko host." (PMID 27762297, 2016). "Thus, it is noteworthy that butyrate induces the differentiation of regulatory T cells in vitro and in vivo, and ameliorated the development of colitis induced by adoptive transfer of CD4(+) CD45RB(hi) T cells in Rag1(−/−) mice." (PMID 25920452, 2015). "Lastly, to test whether the functional defect in CD4cre:PP4f/f Treg cells was the predominant cause for the spontaneous colitis in the CD4cre:PP4f/f mice, we co-transferred WT or CD4cre:PP4f/f Treg cells with WT CD4+CD45RBhigh T cells into RAG1-/- recipients." (PMID 24904742, 2014). "This is in line with previous work showing that both anti-CD90 (Thy-1) depletion in Rag1-deficient mice or use of Rag1.Rorc-double deficient mice, which principally lack IL-23R+ innate lymphoid cells, are similarly resistant to anti-CD40-induced colitis." (PMID 24586521, 2014). "Although activation of NF-kB plays a pivotal role in the activation, differentiation and proliferation of T cells, we observed that transfer of Nod2 deficient naive CD4+CD45RBhigh T cells in Rag1-/- mice did not impair the induction of colitis." (PMID 24324812, 2013). "Additionally, we compared the ability of wildtype C57BL/6 or HVEM-/- and LIGHT-/- CD4+CD45RBhigh T cells to mediate experimental colitis following their transfer into immuno-compromised RAG1-/- hosts." (PMID 21533159, 2011). "To assess the role of IL-23R expression on T cells in the development of colitis, we transferred CD4+CD45RBhi cells isolated from wild-type (WT) or Il23r−/− mice into B and T cell-deficient Rag1−/− mice, with the latter allowing us to restrict IL-23 responsiveness to the innate immune compartment." (PMID 20732640, 2010). "While control Tregs inhibited colitis development, the suppressive potential of oligomycin‐pretreated Tregs was impaired, as the Rag1−/− recipients of CD45Rbhi T cells and oligomycin‐pretreated Tregs showed more severe colitis compared to Rag1−/− recipients of CD45Rbhi T cells and control Tregs." (PMID 41178490, 2026).
colitis (continued). "In Rag1–/– mice, α-DR3 treatment similarly caused a more rapid rate of weight loss, shorter colons, increased number of neutrophils and eosinophils in lamina propria, as well as more severe intestinal pathology during DSS-induced colitis compared with controls." (PMID 31358760, 2019). "Indeed, compared to WT Treg, Maf-deficient Treg do not control the development of colitis induced by the transfer of naïve CD4+ T cells into Rag1−/− mice." (PMID 30992496, 2019). "To validate whether anti-miR-142-5p treatment shows similar effects in mice from a different background, we set up an experiment in which we treated ten male RAG1-/- mice with induced transfer colitis, and compared results to scrambled LNA treatment (experiment #3)." (PMID 29059189, 2017). "It has been proposed that NOD2-/- mice were highly sensitive to Toxoplasma gondii infection and that transfer of naive CD4+CD45RBhigh Nod2 deficient T cells into Rag1-/- recipient mice failed to induce colitis due to a T cell intrinsic defect in proliferation and Th1 differentiation." (PMID 24324812, 2013). "To assess whether T cell intrinsic Nod2 regulates the function of T cells in the induction or prevention of colitis, we transferred Rag1-/- recipient mice with naive CD4+CD45RBhigh and activated/memory CD4+CD45RBlow T cells isolated from NOD2-/- or C57BL/6 mice." (PMID 24324812, 2013). "Moreover, transfer of Sf LN cells into adult Rag1−/− recipients also induced colitis." (PMID 24832045, 2012). "These Foxp3+ cells appear to play a functional role in protection from IL-23-independent inflammation because transfer of Foxp3-deficient T cells to Il23a−/−Rag1−/− hosts induces severe colitis, indistinguishable from disease induced after T cell transfer into IL-23-sufficient Rag1−/− recipients." (PMID 18400195, 2008). "Experiments with Atg7ΔCD4 mice revealed more severe colitis induced by 2,4,6‐trinitrobenzenesulphonic acid (TNBS) enema or by recombination with Rag1−/− mice using CD45RBhighCD4+ T cells." (PMID 40887825, 2025). "Unexpectedly, the expression levels of Numa1 and Rag1 in the DSS group were different from those in the CD and TNBS colitis groups." (PMID 38778086, 2024). "Pretreatment with cefoxitin, a broad-spectrum antibiotic, exacerbates CR-induced colitis and lethality in specific-pathogen-free (SPF) Il22-/- and Rag1-/- mice." (PMID 39630719, 2024). "Two plausible explanations for the distinction between the expression levels of NUMA1/Numa1 and RAG1/Rag1 in human and DSS mouse samples are species differences and the limitations of the DSS-colitis model due to inter-batch variability of DSS." (PMID 38778086, 2024). "Transferring IBD microbiota induces more severe colitis in IL-10−/− mice and enhances naïve CD4+ T cell-induced colitis severity in Rag1−/− mice." (PMID 36076980, 2022). "Next, to determine the effect of Blastocystis ST4-altered microbial communities that was independent of adaptive immunity-mediated microbiota changes on experiment-induced colitis, we performed FMT from ST4-colonized Rag1−/− mice into DSS-treated mice." (PMID 35435504, 2022). "Rag-1−/− mice compared to either FVB/N or C3H/HeN strains, when infected with CR, develop transient colitis and crypt hyperplasia." (PMID 34226497, 2021). "Colonic transcriptomes from unchallenged Rag1 knockout mice and unchallenged C57BL/6 mice were used as control datasets for the T-cell transfer colitis and the rest of the mouse models, respectively." (PMID 34136502, 2021). "We then established Batf−/−Rag1−/− mice via crossing Batf−/− mice with Rag1+/− mice, followed by DSS treatment for colitis induction." (PMID 32796851, 2020). "To further confirm that TRAIL-mediated suppression of colitogenic T cells in the development of colitis is via the TRAIL-R, we adoptively transferred TRAIL-treated splenic CD4+CD25− T cells from WT and TRAIL-R KO mice into Rag1 KO mice to induce colitis." (PMID 31076664, 2019).
colitis (continued). "Next, to investigate the physiological effects of Nfil3-overexpressing Treg cells, we injected Treg cells intraperitoneally into Rag1 knockout (KO) mice, along with naive CD4 T cells, to induce colitis." (PMID 31311918, 2019). "Rag1−/− mice received an adoptive transfer of CD4+CD25−CD45Bhi cells (Teff) from WT or mPGES-1−/− donor mice, and were monitored and evaluated for colitis progression for 10 subsequent weeks after transfer." (PMID 30619314, 2018). "During the development of colitis or CAC, we observed a significantly reduced secretion of IL-17A in the colon of lmp7−/− and rag1−/−lmp7−/− mice as compared to WT and rag1−/− control animals, respectively." (PMID 28881574, 2017). "The overall pathology score was significantly lower in Rag1−/− mice receiving Ccdc88bmut vs. WT CD4+ T cells, demonstrating less severe colitis in the former group." (PMID 29030607, 2017). "To elucidate the impact of RORγt and T-bet expression on the colitogenic potential of T cells, we transferred Rag1−/− mice with CD4+ T cells from C57BL/6 WT, Tbx21−/− or Rorc−/− donors and assessed the development of colitis." (PMID 27193261, 2016). "Intraepithelial ILCs1 are increased in inflamed gut of CD patients and produce high amounts of IFN-γ in Rag1−/− mice treated with anti-CD40, a model of colitis characterized by wasting syndrome and severe intestinal inflammation." (PMID 25061260, 2014). "As expected, RAG-1−/− mice transferred with wt CD4+ T-cells developed colitis and so did transferred RAG1−/−β2i/MECL-1−/−β5i/LMP7−/− mice, with similar severity as RAG1−/−mice." (PMID 24740379, 2014). "In this model, Rag1−/− mice transferred with naive CD4+CD25−CD45RBhi T cells develop wasting disease and colitis with splenomegaly, mesenteric lymph node (MLN) enlargement, and severe leukocytic infiltration of the colon." (PMID 23200826, 2012). "They develop colitis and their LN cells were able to transfer colitis to Rag1-/- recipients, demonstrating the presence CD103-independent mechanism for colitis." (PMID 19272184, 2009). "To determine whether the aggravation of colitis induced by high fructose consumption relies mainly on T-cell inflammation, we established the DSS-induced colitis model using nude mice or Rag1−/− mice." (PMID 40854873, 2025). "Rag1 ko mice served as baseline controls for the mouse model of transfer colitis, while C5BL/6 wildtype mice served as baseline controls for the model of DSS-induced colitis." (PMID 40909203, 2025). "To rule out a role for mutant Tregs in the development of the disease, we injected either WT or KO Tregs into Rag1–/– mice and found that neither group of Tregs induced significant colitis like CD4+ T cell injection did." (PMID 39480507, 2024). "In order to better understand innate immune contributions to IBD, we developed a model of spontaneous 100% penetrant, early onset colitis that occurs in the absence of adaptive immunity by crossing villin-TNFAIP3 mice to RAG1-/- mice (TRAG mice)." (PMID 38512959, 2024). "This colitis was also significantly increased in Rorc-/- x TRAG mice, compared to RAG1-/- mice." (PMID 38512959, 2024). "By contrast, in the colon, SPF MP cells did not induce colitis in GF Rag1−/− mice, whereas GF MP cells did develop colitis in SPF Rag1−/− animals." (PMID 39630890, 2024). "RAG1-/- mice maintain an inner mucus layer largely devoid of microbes and also do not develop colitis." (PMID 38512959, 2024). "Additionally, Rag1–/–RorccreCtnnb1ex3fl/wt and control Rag1–/–Ctnnb1ex3fl/wt mice were challenged with DSS-induced colitis in order to exclude the influence of T cells." (PMID 38561332, 2024). "To better characterize and quantify the role of RoRγt in the histopathological features of colitis in TRAG mice, we applied an 8 point histological scoring system comparing RAG1-/-, TRAG and Rorc-/- x TRAG histopathology along the proximal to distal axis of the colon." (PMID 38512959, 2024).
colitis (continued). "Surprisingly, incoming CD4+ T cells induced lethal colitis in adult Rag1-knockout animals that lacked the TSLP receptor (Rag1KOTslprKO)." (PMID 37427591, 2023). "As expected, no significant change in DSS‐treated colitis by L. intestinalis was detected in Rag1−/− mice." (PMID 37983567, 2023). "In the absence of IL2 expression in Rag1–/– × Rorc-Cre × Il2fl/fl mice, more severe colitis is induced upon adoptive transfer of naïve CD4+ T cells, compared with Rag1–/– × Il2fl/fl mice, demonstrating the relevance of ILC3-derived IL2 in modulating pathogenic T cells." (PMID 35618586, 2022). "To generate a mouse colitis model dependent solely on human TNF expression, we transferred naive T cells isolated from hTNF-KI donor animals into offspring of hTNF-KI mice crossed with Rag1−/− mice 21,22." (PMID 35383266, 2022). "Altogether, these results demonstrate that adoptive transfer of Aβ0/0 Treg cells failed to block colitis induction in Rag1 ko mice, suggesting an impaired function of these cells." (PMID 34211466, 2021). "One research showed that adoptive transfer of naive CD4+ T cells to Rag1−/− recipients will lead to development of colitis; however, adoptive transfer of naive Bcl6−/− CD4+ T cells into Rag1−/− recipient cannot induce Tfh cell differentiation and the development of colitis." (PMID 34471409, 2021). "When intestinal epithelial cell-specific Dclk1-knockout (Dclk1ΔIEC) or Dclk1ΔIEC;Rag1−/− double knockout (DKO) mice were infected with CR and given a single dose of DBZ, they developed barrier defect and severe colitis with higher levels of stromal DCLK1-S, Ly6G, NE, and Notch1." (PMID 34226497, 2021). "It was shown that the neutralization of IL17A in a dextran sodium sulfate (DSS) murine colitis model resulted in elevated tissue damage and T cells, lacking IL17A or IL17R, transferred into RAG-1 deficient mice, led to increased severity of the colitis course." (PMID 33859636, 2021). "To know whether ILC contribute to tissue damage, fibrosis, and/or recovery in colitis, we then used a mAb to deplete ILC in RAG‐1−/− mice." (PMID 32567222, 2020). "To establish further evidence that the protective role of CCL1/CCR8 signaling during acute colitis is primarily driven by innate immune system mediated mechanisms, we overexpressed CCL1 in lymphopenic Rag1−/− mice, which lack T and B cells, but harbor a functional ILC compartment." (PMID 33613532, 2020). "was comparable between circKcnt2+/+Rag1−/− and circKcnt2−/−Rag1−/− mice, suggesting that this colitis discrepancy was not due to increased intestinal colonization by H.h." (PMID 32796851, 2020). "Mechanistically, gene profiling experiments revealed a Th17 response dominated molecular expression signature in colon tissues of IRF4-proficient, colitic Rag1−/− but not in colitis-protected Rag1−/−Irf4−/− mice." (PMID 33584655, 2020). "We and others recently described the importance of IL-10R signaling in macrophages in the prevention of colitis, with Il10rb−/−Rag1−/− mice but not Rag1−/− mice developing colitis upon reconstitution with WT CD4+ T cells." (PMID 30796216, 2019). "We next asked if the reduction of Stat1−/− T cells was dependent on colonic inflammation by transferring unfractionated WT or Stat1−/− CD4+ T cells into Rag1−/− mice, a strain that does not develop colitis when reconstituted with unfractionated WT T cells." (PMID 30796216, 2019). "Similar to chemical-induced IBD, T-cell transfer-induced colitis in Rag1-/- mice were also attenuated by CD69+ Tregs but not CD69−Tregs." (PMID 30185773, 2018). "Indeed, indiscriminate inhibition of COX enzymatic activity with piroxicam accelerates colitis in both IL10−/− mice and during transfer of CD4+ cells from IL10−/− mice into Rag1/− mice." (PMID 30619314, 2018). "We found that Rag1−/− mice lacking functional Ccdc88b recovered from DSS-induced colitis (increased body weight, lower colonic damage, better total pathology scores) faster and more fully when compared to control Rag1−/− mice." (PMID 29030607, 2017).
colitis (continued). "Acute and chronic colitis were induced by administration of DSS or TNBS to wild-type and CCR5−/− mice or adoptive transfer of splenic naïve CD4+ T-cells from wild type or CCR5−/− mice into RAG-1−/−." (PMID 27492684, 2016). "The depletion of CD169+ macrophages in RAG1 KO mice that were crossed with CD169-DTR mice did not ameliorate the clinical symptoms of T-cell-transfer colitis." (PMID 26193821, 2015). "To further investigate the contribution of lymphoid cells to the exacerbated colitis phenotype seen in Rasal3−/− and Arhgef2−/− mice, we tested the ability of B6, Rasal3−/− and Arhgef2−/− naïve CD4+ CD25−CD45RBHi T cells to induce colitis upon adaptive transfer into lymphopenic Rag1−/− mice." (PMID 38200184, 2024). "Upon transfer into Rag1−/− mice, in vitro-induced Th1-like cells accumulate in the colon and mediate spontaneous colitis; however, the transfer of Il23r−/− Th1-like cells did not result in colitis." (PMID 39379604, 2024). "Notably, colitis induced by transfer of WT T cells into TNFf/f x Vil-Cre×Rag1−/− and TNF−/−×Rag1−/− recipients was accompanied by increased proliferation of epithelial cells, in contrast to Rag1−/− mice reconstituted with WT T cells." (PMID 35383266, 2022). "Microbial invasion was not evident on RAG1−/− mice, which also do not develop colitis." (PMID 36162004, 2022). "To determine if the inhibitory ability of rTsPmy-induced Tregs in colitis can be transferred to mice not receiving rTsPmy, we used a well-defined adoptive transfer model of Rag1 KO mice passively receiving Tregs isolated from cLP of Foxp3eGFP reporter mice treated with rTsPmy or PBS." (PMID 34336843, 2021). "However, Itgb8-/- Tregs failed to control ongoing colitis when they were injected two weeks after the transfer of naïve T cells in Rag1-/- mice." (PMID 34302795, 2021). "Since either Rag1−/− mice or wild-type mice, upon the sympathectomy, did not develop colitis, monocyte and macrophage cell populations should be key players in the observed experimental colitis." (PMID 34884737, 2021). "In addition, the phenotype of disease in Rag1−/− mice receiving Nlrp3−/− or Casp-1−/− CD4+ T cells did not resemble the exacerbated colitis observed in mice receiving Asc−/− CD4+ T cells." (PMID 31379813, 2019). "The development of colitis after T cell transfer resulted in a marked shift of the Ly6Clow P3 population to the Ly6Chigh MHCII+/- population (P1/P2) in colon LPL compared to Rag1-/- mice treated with the same type of the diet without T cell transfer in all conditions." (PMID 31276514, 2019). "However, α-DR3 exacerbated the colitis indicated by above indexes in Rag1–/–Rorcgfp/+, but not in Rag1–/–Rorcgfp/gfp mice, suggesting ILC3s are required for the pathogenic effect of α-DR3 in DSS-induced innate colitis." (PMID 31358760, 2019). "In line with this idea, using a T cell independent model of colitis, we showed that mice were fully protected from colitis in the absence of IFNγ (Rag1−/−Ifnγ−/− mice) or in the absence of ILC (anti-Thy1.2 depleted Rag1−/− mice or Rag2−/−RorcGFP/GFP mice), in agreement with previous studies." (PMID 29416538, 2018). "Colitis induced by oral infection with C. rodentium is remarkably reduced in mice lacking both the Rag1 and the SLAMF6 genes compared to their Rag-1-deficient controls, but not in mice that only lack the SLAMF6 gene (single knock out) as compared to their WT littermates." (PMID 26834746, 2016). "Sf mice do not develop colitis and this is most likely due to the weaning condition because Sf.Faslpr/lpr mice that lived beyond weaning develop colitis and transfer of Sf lymph node cells into adult Rag1-/- recipients also induced colitis." (PMID 19272184, 2009). "Moreover, the absence of colitis in A20fl/fl Cd11c-Cre Rag1 mice indicate that the absence of A20 in dendritic cells may led to the overactivation of intestinal T cells in A20fl/fl-CD11c-Cre mice, which may lead to IBD." (PMID 34956195, 2021).